FAM124A (family with sequence similarity 124 member A)
Synonyms: FLJ30707
Tractability: PROTAC: its protein half-life has been measured.
Gene: Protein-coding gene on chromosome 13 (51,222,334 to 51,284,239, forward strand). Ensembl gene ENSG00000150510.
Subcellular location (Human Protein Atlas): Nucleoplasm; Cytosol
Gene Ontology:
Molecular function: protein binding
Genetic constraint (gnomAD): Loss-of-function variants: 23 observed, 19.26 expected, observed/expected ratio (o/e) 1.19, 90% interval 0.86 to 1.68. The upper end of that interval is the gene's LOEUF score, 1.68, which puts it in group 6 of 6, group 1 being the genes least tolerant of losing a copy. Missense variants: 623 observed, 706.24 expected, observed/expected ratio (o/e) 0.88, 90% interval 0.82 to 0.94. Synonymous variants: 287 observed, 307.08 expected, observed/expected ratio (o/e) 0.93, 90% interval 0.85 to 1.03.
Homologues: Orthologues: chimpanzee FAM124A (99% identical), macaque FAM124A (92% identical), guinea pig FAM124A (77% identical), rabbit FAM124A (76% identical), pig FAM124A (75% identical), mouse Fam124a (73% identical), rat Fam124a (73% identical), dog FAM124A (64% identical). Paralogues in human: FAM124B (25% identical).
Diseases named in the same sentence as FAM124A in open-access papers:
FAM124A is named in the same sentence as 1 disease in open-access papers, as found by Europe PMC text mining. Sharing a sentence is not in itself a finding about the gene and the disease.
FAM124A shares sentences with these, for which no sentence is quoted: tumor (1 paper).